IFNG (interferon gamma)
Diseases named in the same sentence as IFNG in open-access papers (continued):
Sharing a sentence is not in itself a finding about the gene and the disease.
lupus (continued). "Both lupus patients and female NZBWF1 mice express elevated levels of several pro-inflammatory cytokines including IFNα, TNFα, IFNγ that may act to differentiate immunosuppressive MDSCs into proinflammatory MDSCs." (PMID 34220829, 2021). "Whereas BAFF/BAFF-R interactions induce IFNγ release by TFH in lupus-prone mice, the production of IFNγ by GC TFH was not modified by in vivo BAFF neutralization in SIV-infected macaques." (PMID 33572146, 2021). "IFNγ has long been known to be elevated in both SLE patients and mouse models of lupus." (PMID 33519824, 2020). "Together, our data suggest that EGR2 positively regulates IFNγ production in MRL-lpr lupus CD4+ T cells, but not in control MRL CD4+ T cells." (PMID 32646370, 2020). "In accordance with our previous reports that DN T cells found in SLE patients and lupus-prone mice produced high levels of IL-178, newly formed DN T cells gained the ability to produce IL-17 but failed to produce IFNγ." (PMID 32503973, 2020). "The proportion of CD4+ and CD8+ T cells did not change; however, an elevated level of IFNγ, which is known to promote lupus in both humans and MRL/lpr mice, was found in the serum of mice treated with vancomycin before disease onset." (PMID 33240280, 2020). "In a mouse model of systemic lupus erythematosus (SLE), it was found that treatment with pan-HDACi trichostatin A (TSA) led to a decrease in mRNA expression of various inflammatory cytokines such as IL-6, IL-2, IL-10, and IFNγ." (PMID 31067680, 2019). "Although the pristane-induced lupus model shows a type I IFN signature and requires IFN I for autoantibody production and disease development, IFNγ is overproduced and plays a crucial role in various other mouse models such as MLR-Faslpr/lpr, Sle1b, and Wiskott-Aldrich syndrome (WAS) chimera mice." (PMID 28408984, 2017). "Similarly, FcγRIIb−/− lupus mice treated with etanercept upregulated cancellous bone volume and cortical thickness and downregulated expression of osteoblast marker genes (OSX, Collagen type I α 1) and serum levels of TNFα, IFNγ, IL-6, and IL-17A." (PMID 38164134, 2023). "Other therapies which target molecules believed to play a role in CLE pathogenesis, such as Janus kinases (JAKs), spleen tyrosine kinase (SYK), interferon γ (IFNγ), IL-12, and IL-23, have been evaluated in lupus clinical trials with skin-specific outcomes but failed to meet their primary endpoints." (PMID 35899214, 2022). "Intraperitoneal route of metformin gave a superior effect on the suppression of IFNγ levels and increasing FOXP3 mRNA expression compared to the oral route, and to the best of our knowledge this was the first study that observed this effect in pristane induced murine model of lupus." (PMID 34386197, 2020). "Further support for the decisive role of IFNγ in murine lupus is demonstrated by the findings that depletion of IFNγ or IFNγ receptor in MRL-lpr and NZBWF1 mice reduced autoantibody production, improved histopathologic scores of kidneys, and promoted the survival of these lupus mice." (PMID 32646370, 2020). "Importantly, we have shown that EGR2 is critical for Th1 differentiation and that inhibition of EGR2 in vitro suppresses IFNγ production only in MRL-lpr lupus CD4+ T cells, but not control MRL CD4+ T cells." (PMID 32646370, 2020). "In contrast, dexamethasone did not alter the expression of CD64 on monocytes from systemic lupus erythematosus (SLE) patients in vitro, while it did inhibit the upregulation of monocytic CD64 induced by IFNγ, IFNα, and IL-12." (PMID 37653557, 2023). "We found that EGR2 inhibition significantly reduced IFNγ production in PMA and ionomycin activated MRL-lpr lupus CD4+ T cells, but not control MRL CD4+ T cells." (PMID 32646370, 2020). "Similarly, systemic lupus erythematosus (SLE) mice without ABCs display defects in T cells, with fewer activated/memory CD4+ T cells and less IFNγ+CD8+ T cells compared to mice with ABCs." (PMID 35298565, 2022).
atherosclerosis (307 papers, 2005 to 2026). A disease characterized by the build-up of fatty material and calcium deposition in the arterial wall resulting in partial or complete occlusion of the arterial lumen. "Elevated interferon gamma (IFNγ) levels are known to be linked with pro-inflammatory responses and atherosclerosis plaque vulnerability due to arterial stenosis suppression." (PMID 39941136, 2025). "By comparison, mouse IgG2a/c in response to IFNγ signaling has been implicated as a major mechanism for the aggravation of atherosclerosis following IRA B-1 cell activation which activates macrophage through high-affinity binding to CD64 (FcγRI)." (PMID 36461105, 2022). "Similar to AD, Th1 cells are associated with worsening of atherosclerosis, as exogenous IFNγ enhances atherosclerosis in Apoe−/− mice." (PMID 35872901, 2022). "Th1 cells are the predominant pathogenic T cell in atherosclerosis, contributing to high levels of IFNγ, which activate macrophages and monocytes and upregulate expression of MMPs, thinning the fibrous cap and increasing risk a plaque rupture." (PMID 35872901, 2022). "Changes in the expression of genes associated with inflammation and atherosclerosis were assessed, including interleukins (IL), interferon-gamma (IFN-γ), TNF-α, a vascular cell adhesion molecule (VCAM), and an intercellular adhesion molecule (ICAM)." (PMID 36142554, 2022). "Mice deficient in IFNγ had a lower atherosclerotic lesion burden, which suggested that IFNγ had pathogenic effects on atherosclerosis." (PMID 33841393, 2021). "IL-18 stimulates the production of interferon gamma (IFN-γ), which in turn is likely to be implicated in the pathogenesis of atherosclerosis." (PMID 29590212, 2018). "Aside from hallmark pro-inflammatory pathways such as MAPK and NF-κB, the top ranked candidates for M(IFNγ) were enriched in various pathways associated with atherosclerosis and other vascular disorders, including Wnt, FGF, adrenergic, IGF, Akt, and ras." (PMID 30303482, 2018). "For example, inhibition of IFNγ-induced STAT1 signaling protects against atherosclerosis development and IFNγ is associated with the development of AT in obese patients and diminishes insulin signaling in human adipocytes." (PMID 22403661, 2012). "The analysis of the transcriptome in biopsies from psoriatic skin lesions and atherosclerotic plaque biopsies indeed shows that TNFα, IFNγ, and IFNγ-induced genes were upregulated to a similar level in psoriasis and atherosclerosis therefore representing putative common pathogenic mechanisms." (PMID 37953417, 2024). "Animal studies showed that IL-10-deficient mice developed significantly more atherosclerosis, with elevated T cell accumulation, IFNγ expression, and reduced collagen content in the lesion, concordant with its role as a potent inhibitor of inflammatory responses." (PMID 33562334, 2021). "Also, atherosclerosis is reduced in ApoE−/− mice deficient in TNFα and IFNγ potentiates atherosclerosis in these mice." (PMID 23560095, 2013). "IFNγ for example causes LPS hypersensitivity and promotes atherosclerosis." (PMID 17997851, 2007). "The interplay between MØ and IFNγ signaling is particularly relevant in the context of atherosclerosis." (PMID 40607379, 2025). "Wild-type mice treated with anti-IFNγ antibodies were also protected from atherosclerosis upon heart transplantation." (PMID 40607379, 2025).
atherosclerosis (continued). "This study investigated the role of MØ STAT1-mediated signaling in atherosclerosis progression through multi-omics integration of IFNγ-induced MØ and expression analysis in human and mouse atherosclerotic lesions." (PMID 40607379, 2025). "Interferon gamma (IFN-γ) is central to adaptive and innate immunity, with elevated levels linked to various cardiac diseases and atherosclerosis." (PMID 41552677, 2025). "Interferon-gamma (IFN-γ) is a pro-inflammatory cytokine primarily produced by T cells and macrophages that plays an important role in the progression of atherosclerosis." (PMID 40243756, 2025). "This is similar to the binding site distribution seen for IFNγ+LPS-induced genes in HMECs and predicts a combined role of IRFs with STATs and/or NF-κB in experimental atherosclerosis as well." (PMID 39840103, 2024). "CD8+ T cells have been also described to exhibit pro-atherosclerotic properties via IFNγ production and macrophage activation, and anti-atherosclerotic properties via B cell modulation; however, knowledge of their role in atherosclerosis is limited." (PMID 38138958, 2023). "Interleukin-6 (IL-6), interleukin-12, and interferon-gamma (IFN-γ) are a few of the several cytokines that have a role in the development of atherosclerosis." (PMID 38292957, 2023). "Activated T-helper 1 (TH1) lymphocytes promote atherosclerosis by stimulating mononuclear phagocytes via IFNγ." (PMID 38138958, 2023). "Reduced Th1 and Th17 cytokines (IFNγ and IL‐17) in the atherosclerosis lesion were also observed in aortic sinus sections." (PMID 36683148, 2023). "Ox-LDLs have other effects in macrophages such as inducing the expressions of IL-12 and IL-18 and Th1 differentiation, as well as increasing the secretion of interferon gamma (IFN-γ) and, with this, the progression of atherosclerosis." (PMID 36829822, 2023). "IFNγ activates macrophages, increasing their inflammatory potential, and during atherosclerosis has a potent proatherogenic effect on plaque formation with deletion of Tbet and IFNγ alleviating this plaque formation in ApoE−/− mice." (PMID 36461105, 2022). "The cytokine interferon‐gamma (IFN‐γ) is a master regulator of innate and adaptive immunity involved in a broad array of human diseases that range from atherosclerosis to cancer." (PMID 35166455, 2022). "The converse is also true; stimulation of PD-1 signalling in mice inhibits atherosclerosis by modulating T-cell activity – reducing interferon-gamma producing CD4 + T cells and increasing atheroprotective IL-10 secreting CD4 + T-cells." (PMID 36461057, 2022). "NK cells represent a potent source of inflammatory IFNγ, and their pathologic role in atherosclerosis had been previously suggested." (PMID 36275758, 2022). "A subpopulation of B-1a cells, termed Innate Response Activator (IRA) B cells, have been found that aggravate atherosclerosis in mice through the production of IFNγ and GM-CSF." (PMID 36461105, 2022). "Th1 cells are characterized by production of IFNγ, which plays a pro-inflammatory role in atherosclerosis." (PMID 36275758, 2022). "In contrast, IL-10 has well-described anti-atherogenic properties and is often associated with regulatory T cells, which can suppress activation and proliferation of immune cells during atherosclerosis, including IFNγ-producing CD4+ T cells." (PMID 34790707, 2021). "It is known that interferon gamma (IFN-γ) can facilitate the progression of inflammatory diseases—for example, inflammatory bowel disease and atherosclerosis." (PMID 34512320, 2021). "Atherosclerosis drives Treg plasticity, resulting in the accumulation of an intermediate dysfunctional Th1-like IFNγ+ phenotype which permits further arterial inflammation." (PMID 33516262, 2021). "IFNγ administration exacerbated AS via increasing the T-cell number within lesions in atherosclerosis-prone apoE-/- mice." (PMID 34658858, 2021).
atherosclerosis (continued). "Atherosclerosis is a chronic autoimmune disease characterized by the accumulation of lipids and immune cells, such as macrophages and pro-atherogenic IFNγ-producing Th1 cells, in the atherosclerotic plaque." (PMID 34790707, 2021). "IFNγ+-producing T cells are major drivers of local and systemic inflammation and have a pivotal role in atherosclerosis development and in CVD." (PMID 32395119, 2020). "Similar findings were observed in other pathologies such as Type I diabetes and atherosclerosis, where interferon gamma, which is produced by NK cells, triggered an excessive, uncontrolled, and unresolved immune response in those diseases." (PMID 33371393, 2020). "During experimental murine atherosclerosis, it was found that Tregs can undergo plasticity and adapt an effector Th1-like phenotype, resulting in the accumulation of IFNγ secreting Treg/Th1 hybrid cells in plaques." (PMID 32650487, 2020). "We found that the exTreg population is composed of memory, IFNγ+ and Tfh cells and that the cell numbers of these subsets were increased in atherosclerosis." (PMID 29545616, 2018). "T cells that expand in pathology and promote development of insulin resistance, atherosclerosis, and hypertension include predominantly IFN-γ-producing Th1 (CD4+) and Tc1 (CD8+) cells, producing IFNγ and TNF, and IL-17 producing Th17 cells." (PMID 28838042, 2017). "CX3CL1 induces tumor necrosis factor alpha (TNF-α), interferon gamma, and interleukin 1 beta (IL-1β) production in chronic obstructive pulmonary disease, pulmonary hypertension, atherosclerosis, RA, HIV infection, and cancer." (PMID 29268768, 2017). "IFNγ is expressed at high levels in atherosclerotic lesions thus playing a pro-inflammatory role in the pathogenesis of atherosclerosis and regulating the functions and properties of all cell types present in the vessel wall." (PMID 27166190, 2016). "ApoE−/− mice fed a western diet have increased atherosclerosis with low dose IFNγ treatment (Bluyssen and Poledne 2015, unpublished results)." (PMID 27166190, 2016). "A role for Th1 cells in promoting atherosclerosis has been inferred because mice that are deficient in either IFNγ receptors or IFNγ itself have smaller lesions, whereas administration of exogenous IFNγ to EKO mice augments atherosclerosis." (PMID 26886778, 2016). "In particular, we found high levels of IL-1β, TNF-α, IFNγ and CD40L, all of which have been associated with the progression of atherosclerosis." (PMID 25548922, 2014). "In animal models, IL17A deficiency was observed to reduce atherosclerosis, decrease the number of macrophages in the atheroma, and inhibit release of monocyte chemoattractant protein 1, IL1b, IL12, and interferon gamma in the plaque." (PMID 28352449, 2014). "Lymphocytes modulate smooth muscle proliferation via interferon gamma which controls the course of luminal narrowing in atherosclerosis." (PMID 24070055, 2013). "Interferon gamma has been suggested to accelerate atherosclerosis e.g. by activating macrophages and increasing their production of nitric oxide and pro-inflammatory cytokines." (PMID 22509262, 2012). "The key role of IFNγ has been confirmed in experimental atherosclerosis whereby ApoE-/- IFNγ receptor-/- mice displayed a substantial reduction in lesion size compared to ApoE-/-." (PMID 21526997, 2011). "However, the precise mechanisms by which STAT1-mediated IFNγ signaling contributes to atherosclerosis progression remain incompletely understood." (PMID 40607379, 2025). "A similar protection of atherosclerosis could also be detected in WT mice treated with anti-IFNγ antibodies upon heart transplantation." (PMID 41155497, 2025).
atherosclerosis (continued). "Additionally, VCAM-1 expression on EC surface can be significantly enhanced by TNF, IL-1β, and IFNγ during atherosclerosis." (PMID 40454002, 2025). "Collectively, we provide detailed insights into MØ-specific IFNγ-activated transcriptional changes, mediated by STAT1-PU.1 co-binding and associated epigenetic changes, and offer the identification of new biomarkers and therapeutic targets in atherosclerosis." (PMID 40607379, 2025). "Accordingly, we provide detailed insights into MØ-specific IFNγ-activated transcriptional changes, mediated by STAT1-PU.1 co-binding and associated epigenetic changes, and offer the identification of new biomarkers and therapeutic targets in atherosclerosis." (PMID 40607379, 2025). "Meanwhile, atherosclerosis-driven dysfunctional/plastic interferon- γ (IFNγ) +C-C motif chemokine receptor 5 (CCR5) + Th1-Tregs in ApoE−/− mice show reduced TIGIT expression, suggesting that TIGIT plays a stabilizing role in Tregs, helping to suppress inflammation." (PMID 39926714, 2024). "CD8+ T cells promote atherosclerosis through two mechanisms, first by leading to vascular inflammation by the secretion of proinflammatory cytokines such as interferon‐gamma (IFN‐γ) and tumor necrosis factor-alpha (TNF-α) and second by increasing apoptotic cell numbers in lesions." (PMID 39463572, 2024). "Heart disease, atherosclerosis, and hypertension are all associated with increased pro-inflammatory cytokines, such as tumor necrosis factor-alpha (TNF-α), interleukin (IL)-1β, IL-6, and interferon-gamma (IFN-γ)." (PMID 37238657, 2023). "In addition, in mouse models of atherosclerosis, the disease seems to be driven by IFNγ-producing CD4 T cells upon antigen recognition on DC/macrophages localized in the arterial wall." (PMID 35903540, 2022). "Inflammatory cytokines including interleukin-1beta (IL-1β), tumor necrosis factor alpha (TNF-α), transforming growth factor-beta (TGF-β), and interferon-gamma (IFN-γ) induce endothelial dysfunction and the acquisition of mesenchymal properties, therefore contributing to atherosclerosis." (PMID 34604359, 2021). "Deletion of IFNγ reduces atherosclerosis in a sex-dependent manner in the rodent model." (PMID 34658858, 2021). "On the one hand, macrophages and T cells play a critical role in atherosclerosis progression by triggering and maintaining proatherogenic innate and adaptive immune responses, involving proinflammatory mediators such as IL-1, IL-6, or IFNγ." (PMID 32395119, 2020). "In addition, it has been demonstrated that SOCS1 is a potent inhibitor of the IFNγ signaling pathway and can prevent atherosclerosis by inhibiting IFNγ signaling." (PMID 31024559, 2019). "The role of IFNγ in atherosclerosis has been extensively studied as has Treg:Th-1 plasticity." (PMID 29545616, 2018). "The reductions in TNFα and IFNγ may also have contributed to the reduced atherosclerosis IL1β and TNFα enhance macrophage-derived foam cell formation by inhibiting macrophage intracellular lipid catabolism." (PMID 23560095, 2013). "Furthermore, murine cardiac allografts sited in IFNγ-/- recipients had reduced transplant atherosclerosis." (PMID 21526997, 2011).